APOBEC3B (apolipoprotein B mRNA editing enzyme catalytic subunit 3B)
Diseases named in the same sentence as APOBEC3B in open-access papers (continued):
Sharing a sentence is not in itself a finding about the gene and the disease.
cancer (continued). "Mutagenesis in cancer cells generated due to the activity of APOBEC family members, and in particular of APOBEC3B, has been a subject of many recent studies." (PMID 29642934, 2018). "Several other cancer types had increased levels of expression of the APOBEC3B gene, but their mean expression levels of APOBEC3A were comparable to the mean APOBEC3A expression across all cancer types." (PMID 29642934, 2018). "Our lab has shown that loss of FHIT expression causes genome instability and provides single-strand DNA substrates for APOBEC3B hypermutation, in line with evidence that FHIT locus deletions occur in many cancers." (PMID 29254236, 2017). "In this family, all APOBEC3s, except for APOBEC3B, APOBEC3D, APOBEC3F, and APOBEC3G, contain only one CDA, which may explain why APOBEC3B is an epigenetic factor in many cancers." (PMID 36203448, 2022). "An increase in the expression of APOBEC3B—but not APOBEC3A—was observed in cancers with ecDNA compared to samples without ecDNA (3.1-fold; q-value < 1 × 10−5)." (PMID 35140399, 2022). "In particular, components of ATR and FA pathways are increased HPV positive OPSCCC cells that also contain enhanced levels of APOBEC3B as compared to HPV negative cancers and normal cells." (PMID 34578402, 2021). "APOBEC3B, a DNA cytidine deaminase, is a known cancer driver gene in the Cancer Gene Census, but there are no literature reports of its stage-specificity in any cancer." (PMID 31277598, 2019). "Human cancer genomes show signatures that provide clues as to etiological agents, e.g., benzo(a)pyrenes in tobacco smoke, ultraviolet light or endogenous APOBEC3A (A3A) or APOBEC3B (A3B) cytidine deaminases." (PMID 29963239, 2018). "APOBEC3B, in addition to other members of the APOBEC3 gene family, has recently been intensively studied due to its identification as a gene whose activation in cancer is responsible for a specific pattern of massively occurring somatic mutations." (PMID 29100317, 2017). "More recently, APOBEC3B and APOBEC3A were also reported to be mutagenic enzymes whose activation in cancer is responsible for specific patterns of massively occurring somatic mutations, referred to as kataegis (from the Greek for “thunderstorm”) or “mutation clusters”." (PMID 29100317, 2017). "Compared with APOBEC3B, the APOBEC3C gene may play a different role in the cancer genome mutagenesis." (PMID 26682542, 2015). "A priori, one would predict that APOBEC3B status would not impact cancer incidence because at least one upstream event is needed to elevate APOBEC3B expression." (PMID 25848704, 2015). "In agreement with observation in cancer cell lines, both the APOBEC3B and APOBEC3C genes show higher expression levels in ER− cancers (P < 2.2 × 10−16 and P < 3.1 × 10−5, respectively, two-sided Wilcoxon rank sum test) relative to ER+ cancers." (PMID 26682542, 2015). "Focusing on cancers with primary tumor location of cervix, anus, penis and head and neck, we found that HPV positive samples had significantly higher expression of several APOBEC3-genes, especially APOBEC3B which was significantly fhigher in anus, penis and head and neck." (PMID 40028540, 2025). "APOBEC3A and APOBEC3B are the only endogenous enzymes that are confirmed to induce these signatures in human cells, with indications that additional APOBEC deaminases may contribute to cancer mutagenesis." (PMID 38254863, 2024). "We obtained a six-gene signature (APOBEC3B, GOLM1, FAM117A, KCNQ1OT1, PCDHB2, and USP43) with the ability to predict overall survival and progression-free survival (PFS), which could translate into a prediction of the response to the cancer treatment received." (PMID 35565183, 2022). "The Pan-cancer analysis of whole genomes (PCAWG) study recently showed that the APOBEC signature accounts for the majority of kataegis events and that it correlates with the expression of APOBEC3B, the number of somatic structural variations and age at diagnosis." (PMID 34316699, 2021).
cancer (continued). "However, the role of APOBEC3B beyond its involvement in inducing DNA damage, DNA replication and proliferation has not been well-characterized in the context of any cancer type." (PMID 32934779, 2020). "The cellular portion of the mechanism may also be relevant to nonviral cancers, where genetic mechanisms often activate the RB/E2F axis and APOBEC3B mutagenesis contributes to tumor evolution." (PMID 30723127, 2019). "Indeed, the extended sequence context in which SBS2 and SBS13 mutations occur in human cancers is predominantly that at which APOBEC3A, rather than APOBEC3B, induces mutations in yeast (TCN preceded by a pyrimidine base rather than a purine)." (PMID 30849372, 2019). "Low expression levels of APOBEC3A in nearly all cancer categories and of APOBEC3B in specific cancer categories may provide high levels of noise in correlation analyses, and therefore, association results for these genes should be interpreted with caution." (PMID 29642934, 2018). "Notably, we observed the significantly positive correlation between the APOBEC3B-mediated mutagenesis and APOBEC3B expression levels in ER+ cancers but not in ER− cancers." (PMID 26682542, 2015). "Accurately determining the conditions under which APOBEC3A and APOBEC3B are expressed in normal and cancerous tissues represents a key challenge in building our understanding of how APOBEC-mediated mutagenesis occurs, and how they might be targeted for cancer treatment." (PMID 39548236, 2025). "Thus, APOBEC3B has different expression levels in different tumor tissues; the expression levels were closely related to the pathological state of the tumor, but the correlation was not consistent across different cancer species." (PMID 35918642, 2022). "Whereas many studies have focused on the molecular roles of APOBEC3B, and to some extent APOBEC3A, possible cumulative effects of action of APOBEC3A, APOBEC3B, UNG, REV1, and FHIT on generation of APOBEC3B-like mutation motifs and on drug sensitivity in cancer have not been clearly elucidated." (PMID 29642934, 2018). "In contrast, in the ER+ cancer cell line MCF-7, we only observed promoter activity at the APOBEC3B, but not at the APOBEC3C and the other APOBEC family genes." (PMID 26682542, 2015). "On the other hand, the substantial up-regulation of APOBEC3B gene and absence of down-regulation of APOBEC3C gene in ER− subtypes suggest that the cytosine deaminase activity for APOBECs may be distinct in cancer subtypes." (PMID 26682542, 2015).
tumor (111 papers, 2013 to 2026). "Two of the eleven members of the APOBEC family, APOBEC3A (A3A) and APOBEC3B (A3B) are responsible for the majority of the APOBEC mutational signatures identified in tumor cells." (PMID 38499542, 2024). "In particular, two members of this subfamily, APOBEC3A (A3A) and APOBEC3B (A3B) have been implicated in causing tumor mutations." (PMID 38499553, 2024). "Further studies are needed to address the mutation features in the FHIT-deficient pre-tumor lesion and tumor models with distinct levels of APOBEC3B and UNG." (PMID 36831487, 2023). "Together, these studies provide the first cause-and-effect demonstration that human APOBEC3B is an oncoprotein capable of causing a wide range of genetic changes and driving tumor formation in vivo." (PMID 36865194, 2023). "Together, these studies provide a cause-and-effect demonstration that human APOBEC3B is capable of driving both tumor initiation and evolution in vivo." (PMID 37797615, 2023). "Among the APOBEC3 enzymes, APOBEC3A (A3A) and APOBEC3B (A3B) are the most likely sources of the overall APOBEC‐driven mutations in human tumours." (PMID 36416305, 2023). "High APOBEC3B expression was also associated with gender (female), tumour size (>5.0 cm), histological grade (G3), and TNM staging (lower expression in TNM I)." (PMID 37568604, 2023). "In a combined analysis of multiple tumor types, APOBEC3B expression was strongly associated with a higher APOBEC3-induced mutation load; APOBEC3A, APOBEC3F, and APOBEC3G showed similar but weaker correlations." (PMID 36978147, 2023). "High APOBEC3B expression has been associated with more tumor infiltrating lymphocytes, and APOBEC3B induction drove a robust T cell-mediated immune response in a mouse model." (PMID 36978147, 2023). "Our study is the first to suggest an association between the expression of APOBEC3B and the level of immune cell infiltration of tumor-associated fibroblasts and CD8+ T cells in some tumors." (PMID 35918642, 2022). "In thisstudy, APOBEC3B expression only moderately increased the tumour mutational burden inKP and urethane-induced lung tumours and was not sufficient to make these tumoursimmunogenic." (PMID 35930804, 2022). "A recent study argued that APOBEC3B-mediated mutations resulted in more neoepitopes in tumour cell vaccines." (PMID 35999267, 2022). "The tumor type with the highest alteration frequency of APOBEC3B was UCEC (> 4%), mainly of the ‘mutation’ type." (PMID 35918642, 2022). "In particular, the APOBEC3B protein with cytosine deaminase activity can lead to base substitutions in tumor-causing genes." (PMID 35918642, 2022). "APOBEC-associated mutations are proposed to drive tumor evolution and disease aggressiveness in lung cancer and high levels of the APOBEC3B protein have been associated with poor outcome in breast cancer." (PMID 33863885, 2021). "APOBEC3B expression was found to be an independent prognostic factor in patients with metastatic urothelial carcinoma, and tumor-infiltrating cytotoxic T cells were associated with APOBEC3B expression." (PMID 33925044, 2021). "The association between APOBEC3B expression and tumor-infiltrating lymphocytes was analyzed using Pearson’s chi-squared test." (PMID 33925044, 2021). "APOBEC3B was significantly associated with infiltrating immune and stromal cell types in the tumor microenvironment." (PMID 33842328, 2021). "Our study results suggested that APOBEC3B was an independent prognostic factor for metastatic urothelial carcinoma and appeared to be associated with TILs, which can represent tumor immunity." (PMID 33925044, 2021).
tumor (continued). "Contrary to a good response expected due to increased tumor mutation burden, these results support the possibility of resistance to ICIs in metastatic urothelial carcinoma by harboring APOBEC3B-mediated mutations." (PMID 33925044, 2021). "Consistent with APOBECs as drivers of tumor escape, the APOBEC3B signature is associated with therapeutic resistance in multiple cancers." (PMID 33772027, 2021). "Our data here show that actively driving mutation in tumor cells to enhance mutational load can be achieved using forced overexpression of APOBEC3B." (PMID 32034147, 2020). "APOBEC3B expression would generate a library of mutated antigens, raising multiple clones of tumor-reactive T cells, thereby reducing the chances of antigen escape." (PMID 32034147, 2020). "This is in sharp contrast to the risks of inducing tumor cell escape from therapy, which has previously been the hallmark of APOBEC3B mutagenesis." (PMID 32034147, 2020). "In conclusion, our results indicate that APOBEC3B mRNA is similarly upregulated in DCIS and IBC, but declines in PIK3CA-mutated IBC, which suggests that APOBEC3B plays a role in the early stages of breast carcinogenesis." (PMID 31357602, 2019). "Probably APOBEC3B expression stimulates mutation process, and accelerates tumor evolution speed, and thus leads to bad prognosis for APOBEC3B high NSCLC." (PMID 29695832, 2018). "Many studies have demonstrated a positive correlation between a defined mutation signature and overexpression of APOBEC3B in many tumor types." (PMID 28572915, 2017). "Analysis of tumour samples from women of European descent has shown that germline APOBEC3B deletion is associated with an increased propensity to develop somatic mutations and with an enrichment for immune response-related gene sets." (PMID 27233495, 2016). "Taken together, these data suggest that germline APOBEC3B deletion is associated with the enrichment of immune response-related gene sets arising from tumour-infiltrating immune cells." (PMID 27233495, 2016). "Our gene expression analysis of fresh frozen tumour samples showed that in germline APOBEC3B deletion carriers, there is corresponding loss of gene expression of the APOBEC3B and this is consistent with previous studies." (PMID 27233495, 2016). "We performed gene expression analysis to investigate the biological processes underlying the loss of APOBEC3B in our tumour samples." (PMID 27233495, 2016). "Three additional SNPs in APOBEC3B showed associations with clinic-pathological features: large tumor size and hormone receptor status." (PMID 26920143, 2016). "For instance, in contrast to kinase activation, which can provide a tumor cell and all of its descendants with a measurable growth advantage, APOBEC3B will cause a different repertoire of mutations in every cell it affects." (PMID 25848704, 2015). "Along with APOBEC3A, APOBEC3B has been implicated in tumor mutagenesis." (PMID 38886582, 2024). "Importantly, we determine that APOBEC3B-induced mutations in hairpin-forming sequences within tumor genomes differ from the DNA stem-loop sequences mutated by APOBEC3A." (PMID 38499542, 2024). "The cytosine deaminase APOBEC3B is implicated in tumor evolution through DNA mutation, but whether it also functions as an RNA editing enzyme has not been studied." (PMID 38001542, 2023). "Thus, the expression level of APOBEC3B is closely linked to the prognosis and survival of patients in some tumor cases, but in different ways." (PMID 35918642, 2022). "Moreover, the unique nuclear localization of APOBEC3B also facilitates mutations to promote tumor development." (PMID 36203448, 2022).
tumor (continued). "We therefore decided to express human APOBEC3B in the KP model toincrease the frequency of mutations in these tumours to promote the generationof neoantigens that could stimulate adaptive anti-tumour immune responses." (PMID 35930804, 2022). "In addition, we also analyzed the relationship between the expression levels of APOBEC3B and tumor mutational burden (TMB) and microsatellite instability (MSI) in all TCGA tumors." (PMID 35918642, 2022). "In this study, we established the KPAR cell line from a single-cell clone ofa KP tumour expressing APOBEC3B which had developed in an immune-deficientbackground and therefore could not undergo immune-editing." (PMID 35930804, 2022). "Tumor-infiltrating cytotoxic T cells associated with APOBEC3B expression." (PMID 33925044, 2021). "Tumor-infiltrating cytotoxic T cells were associated with APOBEC3B expression." (PMID 33925044, 2021). "We especially explored the correlation between APOBEC3B and tumor mutations." (PMID 33842328, 2021). "In this respect, if the APOBEC3B-mutated vaccine induces several different heteroclitic neoepitopes, the T cells responding to these neoantigens will also respond to the unmutated epitopes expressed on the parental tumor cells, as we have shown here." (PMID 32034147, 2020). "Conversely, APOBEC3B-mediated mutation of the cellular immunopeptidome might generate neoepitopes which will prime T-cell responses against the newly immunogenic tumor cells." (PMID 32034147, 2020). "Given that APOBEC3B has been proposed to be an endogenous source of mutations, it is paradoxical that germline loss of the APOBEC3B results in increased propensity to develop tumours with hypermutation." (PMID 27233495, 2016). "Given the role of APOBEC3B as an endogenous mutator, it has been proposed that loss of APOBEC3B may be associated with less aggressive tumour phenotype." (PMID 27233495, 2016). "Elevated APOBEC3B expression was associated with recurrence in the luminal tumor subtype." (PMID 27977754, 2016). "These analyses were done by comparing APOBEC3B mRNA levels and tumor mutation counts." (PMID 25848704, 2015). "Furthermore, TpC* mutations shared among tumours were most frequent in the context of TpC*pA, consistent with the APOBEC3B mutational signature." (PMID 26553077, 2015). "Therefore, we used an immunogenic KRASG12D-driven GEMM derived cell line (KPARG12D) which overexpresses APOBEC3B, a single stranded DNA deaminase that induces high mutational burden and strong anti-tumor responses, resulting in a model that is overall more faithful of human disease." (PMID 39533328, 2024). "Furthermore, we report that germline APOBEC3B deletion appears to be associated with an enrichment of immune response genes and that this may arise from the enrichment and activation of tumour-infiltrating immune cells." (PMID 27233495, 2016). "Additional work is likely to yield APOBEC3B inhibitors, and such molecules may have therapeutic merit in high-risk individuals and/or as a post-operative adjuvant to limit further tumor evolution and improve the durability and efficacy of existing therapeutics." (PMID 25848704, 2015). "Understanding the relationship between APOBEC3B activity and cyclic hypoxia in the tumor microenvironment is also important." (PMID 41373684, 2025).